TRIM51G (tripartite motif-containing 51G)
Synonyms: TRIM51GP
Gene: Protein-coding gene on chromosome 11 (48,975,498 to 48,983,885, reverse strand). Ensembl gene ENSG00000220948.
Subcellular location (Human Protein Atlas): Vesicles; Nucleoli
Gene Ontology:
Molecular function: ubiquitin protein ligase activity; zinc ion binding
Biological process: innate immune response; regulation of gene expression
Cellular component: cytoplasm
Genetic constraint (gnomAD): Loss-of-function variants: 7 observed, 9.9 expected, observed/expected ratio (o/e) 0.71, 90% interval 0.4 to 1.33. That is too few expected variants to judge how well the gene tolerates losing a copy. Missense variants: 212 observed, 168.32 expected, observed/expected ratio (o/e) 1.26, 90% interval 1.12 to 1.41. Synonymous variants: 59 observed, 51.4 expected, observed/expected ratio (o/e) 1.15, 90% interval 0.93 to 1.43.
Homologues: Orthologues: chimpanzee TRIM51G (94% identical). Paralogues in human: TRIM51 (87% identical), TRIM49B (72% identical), TRIM49 (71% identical), TRIM49C (71% identical), TRIM49D1 (70% identical), TRIM49D2 (70% identical), TRIM43 (49% identical), TRIM43B (49% identical), TRIM64 (44% identical), TRIM64B (44% identical), TRIM64C (43% identical), TRIM77 (42% identical), and 68 more.